ALB (albumin)
Diseases named in the same sentence as ALB in open-access papers (continued):
Sharing a sentence is not in itself a finding about the gene and the disease.
Hypertension (continued). "CKD (estimated glomerular filtration rate < 90 mL/min/1.73m2 or albumin/creatinine ≥3 mg/mmol) and hypertension (systolic or diastolic blood pressure ≥ 95th percentile for age, sex, and height) prevalence 6 years after surgery was estimated." (PMID 32500246, 2020). "Lipid-lowering therapy in rat models of hypertension can reduce urinary albumin excretion rate (UAER)." (PMID 32256962, 2020). "There were significant differences in DR severity, age, uric acid, albumin and more hypertension events than in other studies." (PMID 33374974, 2020). "Treatment with AB seed extracts also reduced blood pressure, the hypertension biomarker renin, and DN biomarker levels (creatinine, urea, creatin, and albumin)." (PMID 32825710, 2020). "The univariate logistic regression analysis showed that the age, comorbidity, hypertension, lymphocyte count, neutrophil count, NLR, albumin and CRP were associated with the disease severity of COVID-19." (PMID 33110593, 2020). "There were significant differences between the two groups with respect to age, weight loss, habitual alcohol use, ASAPS grade, DM with insulin use, hypertension, serum albumin, serum creatine, clinical tumor depth (cT), and clinical lymph node metastasis (cN)." (PMID 31583502, 2020). "Age, sex, hypertension, preoperative hematocrit, eGFR, serum albumin and C-reactive protein level, intraoperative MAP, C.I. and SvO2 reduction below each cut-off of ROC analysis were considered as covariables." (PMID 33189145, 2020). "Since obesity and hypertension are major risk factors of CVD, we postulated a possible relationship with albumin and creatinine." (PMID 32231008, 2020). "After adjustment for VAT, HDL, LDL, urine albumin, liver fat, GFR and hypertension the association between glycemic status and renal volumes decreased and was only significant for prediabetes and sinus volume (ß = 4.0 95% CI [0.4, 7.6]; p<0.05)." (PMID 32074103, 2020). "Compared with the reference group, the change over time of albumin for patients with cerebrovascular accident, heart failure, chronic obstructive pulmonary disease, hypertension, ischemic heart disease, and ischemic stroke was significantly positive." (PMID 32295526, 2020). "The diabetic patients showed the following: less smoking, higher serum albumin, lower eGFR, more hypertension, more kidney disease, and longer waiting time for surgery than nondiabetic patients." (PMID 32351563, 2020). "The sarcopenia group had significantly lower BMI; lower levels of hemoglobin, ALT, γ-GTP, creatinine, and albumin; lower rates of obesity, hypertension, bicycle use; and lower number of daily conversations than the non-sarcopenia group did." (PMID 33154439, 2020). "Current UK guidelines recommend routine testing of creatinine, urea, and electrolytes, lipid profile, HbA1c, and urine albumin to creatinine ratio in patients with hypertension." (PMID 33278890, 2020). "The BENEDICT study indicated a significant decline in the risk of microalbuminuria in patients with hypertension and T2DM with normal albumin levels in the urine with long-term treatment of trandolapril plus verapamil and trandolapril alone." (PMID 32964020, 2020). "Capillary albumin filtration (CAF) is an early diabetic complication, associated with neuropathy and hypertension." (PMID 32825710, 2020). "CKD was independently associated with hyperuricemia and total cholesterol in females, and with hyperuricemia, hypertension, and serum albumin in males." (PMID 31818273, 2019). "Recently it has been reported to potentially be involved in hypertension, polycystic ovary syndrome, and urinary albumin excretion and renal function, which indicates it is a pleiotropic hormone." (PMID 30929133, 2019). "Compared with non-CKD patients with AS, male CKD patients had more common hyperuricemia and hypertension, higher total cholesterol and triglyceride levels, lower albumin levels, higher ESR level, and more common renal dysfunction." (PMID 31818273, 2019).
Hypertension (continued). "Grip strength, hypertension, and dyslipidemia showed inverse relationships with low serum albumin levels and low BMIs." (PMID 31196057, 2019). "The single step STNx surgery was well-tolerated and resulted in clinically relevant outcomes including hypertension, increased urinary albumin:creatinine ratio, and significantly increased serum creatinine, phosphate and urea." (PMID 31803059, 2019). "Male CKD patients had more frequent hyperuricemia, hypertension and HLA-B27 positivity, higher total cholesterol and triglyceride levels, lower albumin levels, higher ESR and more common renal dysfunction compared with non-CKD patients." (PMID 31818273, 2019). "The presence of hyperuricemia was a strong predictor of renal involvement for both genders of AS patients, while hypertension and low serum albumin are specific predictors for CKD only in male patients." (PMID 31818273, 2019). "Hypertension and dyslipidemia showed an inverse relationship with serum albumin levels below 4.4 g/dL and a BMI below 21.0 kg/m2." (PMID 31196057, 2019). "These included initial proteinuria of more than 1g/d, hypertension, renal impairment (eGFR <60mL/min), hypoproteinemia (serum albumin <35 g/L), hyperuricemia (serum uric acid >420μmol/L), Yang-deficiency BC, and blood-stasis BC at the time of renal biopsy." (PMID 31341498, 2019). "It was identified that the predictors of AKI among critically ill patients from a single-centre Brazilian ICU at admission included a history of hypertension, high serum creatinine and low serum albumin concentrations, and high APACHE II and SAPS 3 scores." (PMID 31792326, 2019). "We validated this method by using an established rat model of proteinuria and hypertension which demonstrate high levels of oxidized albumin and 8-isoprostane." (PMID 31197181, 2019). "In contrast, the percentages of participants who consumed alcohol, hypertension patients, means of HbA1c, creatinine, urea and urine albumin/creatinine ratios (ACR) were higher in the DN patients than that in controls." (PMID 31798690, 2019). "The variables suggested for the final model using the BMA algorithm included age, hypertension, cerebrovascular disease, potassium, albumin, cholesterol, triglycerides, integrase inhibitors, and Non-NRTI." (PMID 30995263, 2019). "Previous studies involving rats with high blood pressure have found several regions of the genome that contribute to high levels of albumin in the urine, including one on chromosome 6." (PMID 30900988, 2019). "Patients in the group C showed lower incidences of atrial fibrillation and living donor LT; lower levels of hemoglobin, sodium, and albumin; higher rates of hypertension; higher MELD scores; and were more likely to be female." (PMID 30365563, 2018). "In multivariable analysis, hypertension, preoperative albumin level, and intraoperative synthetic colloid infusion were associated with the incidence of postoperative AKI." (PMID 30142190, 2018). "They had more arterial hypertension, more dyslipidemia according to similar blood lipids despite twice more treated by statins, more frequent abnormal albumin excretion and estimated glomerular filtration rates, and more previous cardiovascular events." (PMID 29884175, 2018). "Among black men, hypertension (aOR = 1.7, 95% CI: 1.1–2.7) and adverse serum albumin levels (aOR = 1.7, 95% CI: 1.0–2.9) predicted depression, while high total cholesterol was associated with depression among black women (aOR = 1.6, 95% CI: 1.0–2.7)." (PMID 30154326, 2018). "The 32 patients with acute tubulointerstitial injury were older and presented with higher level of urinary protein excretion, lower level of serum albumin, lower level of eGFR, higher percentage of hypertension, and lower level of hemoglobin." (PMID 30153817, 2018).
Hypertension (continued). "Quantitative analysis of urinary albumin concentration variation showed a statistically significant correlation, at the univariate analysis, with baseline urinary albumin values (p < 0.001) and hypertension." (PMID 30362663, 2018). "In this review, the data regarding copeptin with kidney function (evaluated as glomerular filtration rate, increased albumin/protein excretion or both) and hypertension with regard to performed studies, prognosis and pathogenesis was summarised." (PMID 28638629, 2017). "Due to the differences in the baseline characteristics between the CR and NCR patients, we carried out subgroup analysis according to the ratios of males, hypertension and albumin." (PMID 28358842, 2017). "Another study of 1928 patients showed male gender (odds ratio (OR) 3.55), older age at diagnosis of SMR (OR 1.04), hypertension (OR 0.46), serum calcium (OR 2.06) and lower serum albumin (OR 0.23) to be significantly correlated with pre-operative CKD." (PMID 28081704, 2017). "Age, WBC, MPV/PC ratio, albumin level, uric acid level, and prevalence of hypertension and smoking were significantly different among the three sTIPS groups." (PMID 29108310, 2017). "The recommended therapeutic regimens for DN worldwide include controlling blood glucose and hypertension and reducing urinary albumin and blood lipids." (PMID 29250558, 2017). "Hypertension leads to increased glomerular filtration pressure, thereby promoting abnormal glomerular permeability that enables albumin ultrafiltration." (PMID 28899432, 2017). "The clinical information was well matched except for albumin and the ratios of gender and hypertension." (PMID 28358842, 2017). "Mean RDW quartile, age, hypertension, albumin level, Charlson Comorbidity Score and CRP level were identified as potential risk factors for cerebral infarction in the univariate Cox proportional hazard model." (PMID 29141483, 2017). "In comparison to the rest, the participants with a persistent episode of MS were younger, had higher percentages of obesity and dyslipidaemia, a lower percentage of high blood pressure and impaired fasting glucose and also urinary albumin excretion was lower." (PMID 28545089, 2017). "At univariate analysis, patients with septic shock were significantly older, a higher proportion had hypertension, lower platelet count and serum albumin level, higher CRP and PCT level, and higher positive blood culture rate." (PMID 27256181, 2016). "Albumin TER is increased by hypertension (from 5.6 % per hour to 7.6 % per h) and plasma volume decreases by up to 10 %." (PMID 27338619, 2016). "Apart from hypertension, many complications associated with HAC in humans are also linked with an increased urinary albumin excretion rate." (PMID 27340403, 2016). "Patient-level factors associated with increased NTHC use were male gender, history of angina, pulmonary edema, COPD, hypertension, increasing distance from dialysis facility, higher serum phosphate, lower serum albumin and later calendar year." (PMID 26920700, 2016). "An albumin level < 3.3 gm/dL yielded a 35% sensitivity and 87% specificity for predicting systemic hypertension in this sarcoidosis cohort." (PMID 27433355, 2016). "Based on the final model, female gender, and increase in the factors of body weight, dietary carbohydrate, and the blood levels of albumin, glucose, triglycerides, and cholesterol significantly influenced hypertension in respondents." (PMID 29367559, 2016). "Low albumin is related to overhydration and, as a result, high blood pressure and left ventricular hypertrophy." (PMID 26885251, 2016). "These include the duration of DM, insulin treatment, high blood pressure, higher serum lipids, and high glycated hemoglobin urinary albumin excretion." (PMID 27200379, 2016). "The incidence of positive urine dipstick albumin was higher among the elderly (≥65 years old) and those with elevated serum creatinine, high HbA1c (≥7.2%), or high blood pressure in both analyses." (PMID 26808136, 2016).
Hypertension (continued). "Urinary albumin is an independent predictor of hypertension and increases in blood pressure in the general population even in the normal range below the threshold defined for microalbuminuria." (PMID 25674745, 2015). "When groups were divided above and below the 75th percentile of HOMA-IR they were similar in age, gender, systolic and diastolic blood pressure, HbA1c, serum creatinine, urinary albumin/creatinine ratio, lipid profile, presence of hypertension and smokers." (PMID 26753001, 2015). "Age, hypertension, initial eGFR, plasma hemoglobin, serum uric acid, htTKV, random urine albumin to Cr ratio, urinary AGT/Cr were included in the final model." (PMID 26092580, 2015). "Those in the frail group had an increased risk of low HDL-C, hypertension, high heart rate, high WCC, low FEV1, low haemoglobin, poor renal function (low eGFR), low albumin, low ALT, high GGT, high ALP, high phosphate and low sodium." (PMID 25480883, 2015). "In conclusion, urinary albumin is a novel predictor of future hypertension and increases in blood pressure in the general population." (PMID 25674745, 2015). "Some risk factors (HDL-C, hypertension, WCC, FEV1, renal function and albumin) were also associated with being pre-frail." (PMID 25480883, 2015). "Other variables associated with the disagreement between REGICOR and ADVANCE equations were the presence of retinopathy, arterial hypertension with drug treatment, tobacco consumption, pulse pressure, and urinary albumin excretion." (PMID 26464076, 2015). "Albumin-adjusted serum calcium, hypertension (indexed by SBP) and albuminuria (indexed by Alb/Cr) had similar predictive performance for LVH which evaluated by AUCs in ROC curve (0.617, 0.597 and 0.668, respectively)." (PMID 25924883, 2015). "Hypertension prevalence, urinary albumin excretion and albuminuria (≥30 mg/gCr) prevalence were also significantly lower in drinkers with the ALDH2 *2 allele compared with that of other groups." (PMID 26599441, 2015). "This probably reflected the exposure to high blood pressure because both albumin and calcium levels were decreased on the 0.03% diet." (PMID 26077568, 2015). "Levels of butyrylcholinesterase showed a significant correlation with albumin, hypertension, hypercholesterolemia, and weak but significant inverse associations with EuroSCORE, ECMO duration, aspartate aminotransferase (ASAT), and γ-glutamyltransferase." (PMID 24479557, 2014). "Severe preeclampsia was diagnosed as the patient had hypertension with epigastric pain (stretching of liver capsule) and headache (sign of cerebral edema) and urine albumin was +2 by dip stick test." (PMID 25548684, 2014). "These include the use of hypertension, glycated haemoglobin and cholesterol data in the economic modelling for vascular checks; and urinary albumin and creatinine data supporting the calculation of the human and economic costs of CKD." (PMID 25114791, 2014). "The patients with cTNFR1 level within the highest tertile had older age, higher sCr level, proteinuria, hypertension, and advanced pathologic stage but lower eGFR and albumin level than those with cTNFR1 level within the other tertiles." (PMID 25098821, 2014). "In patients with hypertension and albumin: creatinine ratio ≥ 30 mg/mmol, Angiotensin Converting Enzyme inhibitors or Angiotensin Receptor Blockers should be prescribed." (PMID 24955116, 2014). "It was shown, that patients with primary aldosteronism had a higher urinary albumin excretion than patients with essential hypertension that were matched for mean arterial pressure." (PMID 24612948, 2014). "In patients with T2DM and hypertension, urinary albumin is a key prognosticator of both renal and cardiovascular outcomes, with even low levels of albuminuria being associated with progressive renal dysfunction and increased risk of cardiovascular mortality." (PMID 23570327, 2013).
Hypertension (continued). "Age- and sex-standardized prevalence rates were computed for each of the following: type 2 DM, obesity, hyperlypidaemia, hypertension, hyperinsulinemia, elevated albumin/creatinine ratio (ACR), metabolic syndrome, and cardiovascular disease." (PMID 23390466, 2012). "Elevations in albumin excretion are indicative of glomerular injury mainly due to type 2 diabetes or hypertension." (PMID 22995288, 2012). "High normal values of urine albumin-to-creatinine ratio (UACR) have been reported to have predictive values for hypertension, incident stroke, and higher mortality in the general population." (PMID 22995288, 2012). "The exit criteria in the pathway, include hypertension, increased urine albumin:creatinine ratio, reduced serum albumin, reduced glomerular filtration rate and persistent macroscopic haematuria." (PMID 22235302, 2012). "Agarwal and colleagues demonstrated that albumin excretion was significantly elevated in rats with hypertension and that 16 weeks of aerobic exercise training was able to decrease albuminuria." (PMID 23144989, 2012). "Urinary albumin content is influenced by several factors such as intensive physical activity, the menstrual cycle, infection of the urinary system, hypertension and other nephropathies." (PMID 20205888, 2010). "Our goal was to evaluate the effect of a commonly used calcium channel blocker, amlodipine, and an angiotensin converting enzyme inhibitor, lisinopril on urinary albumin excretion in patients with mild to moderate essential hypertension." (PMID 20535265, 2010). "Albuminuria can be indicative of kidney disease, hyperglycaemia, and hypertension, with micro-albuminuria defined as levels of albumin in urine greater than 30 mg/L but lower than 300 mg/L in 24 hours, and gross albuminuria as levels exceeding 300 mg/L." (PMID 19806223, 2009). "The network is characterized by a high level of connectivity between DKD (with high 24 h-urine albumin and serum creatinine), high blood pressure (and anti-hypertensive treatment), diabetic retinopathy and death." (PMID 19804653, 2009). "There was evidence of renal dysfunction in 17 (32%), including ten (19%) with a low GFR (< 80 ml/min/1.73 m2SA), six (11%) with hypertension and five (9%) with increased urinary albumin excretion." (PMID 1329909, 1992). "Confounding variables, including age, body mass index (BMI), waist-to-hip ratio, family history of hypertension, alcohol consumption, smoking, blood urea nitrogen, creatinine, protein, and albumin levels, were used for adjustment in the multiple regression analysis." (PMID 41598580, 2026). "aeruginosa, creatinine, hypertension, liver disease, albumin, platelets, and derived indices." (PMID 42194507, 2026). "LASSO regression identified prostate volume, blood glucose, low-density lipoprotein, triglycerides, urinary leukocyte count, hypertension, Prostate Imaging-Reporting and Data System score, platelet-to-lymphocyte ratio, albumin, the fPSA/tPSA ratio, and PHI as candidate variables." (PMID 41970982, 2026). "The results revealed that the following variables had a p value < 0.05: hypertension, hyperlipidemia, ASA class, presence of urinary catheters, age, hemoglobin, blood urea nitrogen, eGFR, albumin, NLR, blood loss, total fluid infusion, fasting times for solids, and NRS score." (PMID 41214856, 2025). "Furthermore, it is unlikely that there is a direct relationship between the URAT1 inhibitory effect of dotinurad and blood pressure, given that dotinurad effectively lowers urinary albumin in patients with hypertension." (PMID 40839334, 2025). "However, the negative correlation between serum calcium and glucocorticoid-induced hypertension was unaffected after serum albumin was considered a confounder for adjustment." (PMID 40290310, 2025).